VCY (variable charge Y-linked)
Description:
May mediate a process in spermatogenesis or may play a role in sex ratio distortion.
Synonyms: BPY1; VCY1A; VCY1
Gene: Protein-coding gene on chromosome Y (13,985,772 to 13,986,473, reverse strand). Ensembl gene ENSG00000129864.
Gene Ontology:
Molecular function: protein binding
Biological process: brain development
Homologues: Paralogues in human: VCY1B (100% identical), VCX3B (90% identical), VCX3A (89% identical), VCX (87% identical), VCX2 (85% identical).
Diseases named in the same sentence as VCY in open-access papers:
VCY is named in the same sentence as 4 diseases in open-access papers, as found by Europe PMC text mining. Sharing a sentence is not in itself a finding about the gene and the disease. The quoted sentences say what the papers report.
latent infection (1 paper, 2025). "Our data provide important insights into the role of VCY in PFV life cycle, which will aid in understanding the mechanisms underlying retroviral latent infection." (PMID 40459262, 2025).
VCY also shares sentences with these, for which no sentence is quoted: Azoospermia (2 papers); male infertility (1); schizophrenia (1).